KRTAP5-10 (keratin associated protein 5-10)
Description:
In the hair cortex, hair keratin intermediate filaments are embedded in an interfilamentous matrix, consisting of hair keratin-associated protein (KRTAP), which are essential for the formation of a rigid and resistant hair shaft through their extensive disulfide bond cross-linking with abundant cysteine residues of hair keratins. The matrix proteins include the high-sulfur and high-glycine-tyrosine keratins.
Synonyms: KRTAP5.10
Tractability: No criterion of Open Targets' tractability assessment is met for any kind of drug.
Gene: Protein-coding gene on chromosome 11 (71,565,563 to 71,566,735, forward strand). Ensembl gene ENSG00000204572.
Pathways (Reactome):
Developmental Biology: Keratinization
Gene Ontology:
Cellular component: cytosol
Genetic constraint (gnomAD): Loss-of-function variants: 2 observed, 6.38 expected, observed/expected ratio (o/e) 0.31, 90% interval 0.13 to 0.99. That is too few expected variants to judge how well the gene tolerates losing a copy. Missense variants: 219 observed, 243.13 expected, observed/expected ratio (o/e) 0.9, 90% interval 0.81 to 1.01. Synonymous variants: 76 observed, 91.25 expected, observed/expected ratio (o/e) 0.83, 90% interval 0.69 to 1.01.